GSTM2P1 (glutathione S-transferase mu 2 pseudogene 1)
Gene: Processed pseudogene on chromosome 6 (111,046,868 to 111,047,521, reverse strand). Ensembl gene ENSG00000218803.
Diseases named in the same sentence as GSTM2P1 in open-access papers:
GSTM2P1 is named in the same sentence as 1 disease in open-access papers, as found by Europe PMC text mining. Sharing a sentence is not in itself a finding about the gene and the disease. The quoted sentences say what the papers report.
steatosis (1 paper, 2018). Increased lipid within the cytoplasm of cells. "As expected from previous works, steatosis per se down-regulated the expression of several phase I and II XMEs of HepaRG cells, with some exceptions such as CYP2E1, ALDH1A3 and GSTM2P1 whose expression was increased." (PMID 29654281, 2018).